CRP (C-reactive protein)
Diseases named in the same sentence as CRP in open-access papers (continued):
Sharing a sentence is not in itself a finding about the gene and the disease.
periodontitis (continued). "Statistically, patients with a high rate of teeth diagnosed with severe periodontitis are more likely to have higher hs-CRP level." (PMID 33424972, 2020). "The similarity between groups of individuals with normal and altered CRP serum levels regarding age is a strong point of the present study, favoring the analysis of the relationship between periodontitis and CRP." (PMID 32994872, 2020). "Significant differences in the level of CRP were present on days 1 and 7 between the periodontitis and GSE groups, with higher values of CRP in the periodontitis group (P<0.0002, P<0.01)." (PMID 33456610, 2020). "The presence of proinflammatory cytokines, such as IL-1β, TNF-α, and CRP, together with the presence of β-amyloid were found in the brain tissues of mice where periodontitis was induced by the inoculation of P. gingivalis in the periodontal tissue." (PMID 32054121, 2020). "The purpose of this study was to evaluate the relationship between CRP levels and the number and proportion of teeth that showed with ≥5 mm PD in chronic periodontitis." (PMID 33424972, 2020). "Serum CRP levels in HD patients with advanced periodontitis have been reported to be significantly higher (p < 0.05) than in those without periodontitis." (PMID 31382656, 2019). "For instance, in 2010 Chen Lei and coworkers provided data showing that periodontitis correlated with increased levels of glycated hemoglobin (HbA1c) and CRP observed in DM patients." (PMID 30897827, 2019). "In contrast, other investigators have reported that serum CRP levels in HD patients with treated chronic periodontitis (n = 43) were similar (p = 0.634) to untreated patients (n = 30)." (PMID 31382656, 2019). "In the stepwise multivariate regression model, for the whole sample (periodontitis and healthy controls), all potential confounding variables (age, gender, BMI, and CRP) were inserted." (PMID 31817862, 2019). "In contrast, some studies have detected an association between periodontitis/alveolar bone loss and measurements of RA disease activity/severity such as DAS28, CRP, HAQ, tender joint count and/or joint space narrowing scores." (PMID 31072030, 2019). "One Indian study revealed that patients with periodontitis had a higher level of high-sensitive (hs)-CRP than those who were suffering from gingivitis and with healthy gingiva." (PMID 30823670, 2019). "In univariate models, periodontitis (p = 0.034), CHD (p < 0.001), and CRP (p < 0.001) were significantly associated with MAA." (PMID 31805680, 2019). "The present study found that patients with periodontitis showed higher median CRP levels compared to healthy controls." (PMID 31817862, 2019). "The results revealed a positive and significant relationship between periodontitis and CRP among the HD population." (PMID 31683838, 2019). "Markers of systemic inflammation, including C-reactive protein and interleukin 6, are surrogate markers of atherosclerotic vascular disease and are increased in patients with periodontitis." (PMID 30314398, 2018). "NE and CRP levels in aggressive periodontitis were found to be elevated compared to chronic periodontitis." (PMID 29484548, 2018). "The data showing almost identical mean CRP levels in the subgroups of patients with gingivitis and periodontitis are particularly noteworthy." (PMID 30043933, 2018). "Subsequently, various studies showed that patients with less severe oral infections, such as chronic periodontitis, also have higher serum CRP levels than unaffected subjects." (PMID 29986441, 2018). "Oral infections, including gingivitis, periodontitis, and endodontic lesions consistently elevate systemic levels of C-reactive protein (CRP), which is a sensitive biomarker for systemic inflammation." (PMID 29986441, 2018). "A recent study compared NE and CRP levels in patients suffering from a similar severity of untreated aggressive and chronic periodontitis." (PMID 29484548, 2018).
periodontitis (continued). "For the present serum killing experiment we chose ChoP-positive and ChoP-negative strains of serotype-a and serotype-b and the CRP concentration (5 μg/ml) within the range observed in periodontitis patients’ blood." (PMID 30056510, 2018). "Chronic periodontitis increases the amount of the systemic inflammatory mediators C-reactive protein (CRP) and interleukin-6 (IL-6), as well as total cholesterol and low-density lipoprotein (LDL) cholesterol levels." (PMID 30126459, 2018). "Patients with periodontitis have higher levels of CRP and SAA and lower levels of serum albumin compared with healthy population." (PMID 28326084, 2017). "Meta-analyses and systematic reviews of the relationship of CRP to periodontitis have shown consistently higher CRP levels in patients than in controls." (PMID 28431542, 2017). "C-reactive protein (CRP) was significantly (P < 0.05) higher in the GCF of the periodontitis group while interleukin (IL)-8 was significantly (P < 0.01) higher in the GCF of the healthy group." (PMID 29163429, 2017). "It has been reported in (systematic) reviews that successful treatment of periodontitis is accompanied by a decrease in systemic markers of inflammation such as CRP or leukocyte counts." (PMID 28190975, 2017). "In the present study, significantly higher levels of CRP were observed in the periodontitis group while IL-8 was higher in the healthy group, but these results are different from those of previous studies." (PMID 29163429, 2017). "Periodontitis acts as a reservoir of bacterial lipopolysaccharides (LPS), which induces the production of CRP." (PMID 29017560, 2017). "Such relationship among this pathogen and the high levels of CRP clarify the positive correlation already described in a study, in which the patients with severe periodontitis have increased serum levels of CRP when compared with unaffected control population." (PMID 29085294, 2017). "Among the pathogens related to periodontitis, the P. gengivalis has been related to the levels of CRP found in the aged patients." (PMID 29085294, 2017). "Indeed, periodontitis is associated with systemic oxidative stress and a reduced global antioxidant capacity, which suggests that oxidative stress in patients with periodontitis could be closely linked to the biomarker of inflammation, including C-reactive protein." (PMID 26941889, 2016). "Thus, cross sectional studies have shown that the presence of periodontitis, or antibodies to common periodontal bacterial flora, are associated with an increase in a systemic proinflammatory state characterized by an increase in serum CRP; TNFα and TNFα/IL10 ratios in participants with AD." (PMID 26963387, 2016). "During periodontitis, salivary CRP levels increase and its decrease indicates a successful anti-inflammatory treatment." (PMID 27143814, 2016). "Slade et al9 and Megson et al10 reported increased serum levels of C-reactive protein (CRP) in patients with periodontitis." (PMID 27651883, 2016). "Plasma IgG titers to the three periodontal pathogens, CRP levels, severe periodontitis condition and confounders of MS were evaluated for the outcome of MS from final logistic regression models." (PMID 26871443, 2016). "A number of studies have demonstrated that the CRP levels are higher in periodontitis patients than in control subjects." (PMID 26871443, 2016). "nucleatum had significantly increased circulating CRP levels (p = 0.020) compared to controls while the mice with induced periodontitis had increased levels of IL-6 (p = 0.047) and IL-8 (p = 0.105)." (PMID 25806806, 2015). "Serum elastase and CRP were significantly elevated in patients with untreated aggressive periodontitis compared to healthy controls as well as systemic inflammatory burden." (PMID 26346216, 2015).
periodontitis (continued). "Concentrations of CRP, eotaxin, and MCP-1, in addition to years of smoking and age, were significantly associated with periodontitis, whereas more own teeth and high education were associated with being periodontally healthy." (PMID 26241961, 2015). "Other studies showed increased CRP levels in patients with chronic periodontitis compared to patients with gingivitis." (PMID 26346216, 2015). "In systematic reviews and meta-analyses of CRP protein in relation to periodontitis, CRP levels were consistently higher in patients than in controls." (PMID 26644840, 2015). "We compared and evaluated the systemic levels of CRP in the peripheral blood samples of patients with chronic and aggressive periodontitis, gingivitis, and gingival recessions." (PMID 26346216, 2015). "Activity of S100A12 and C-reactive protein can be markers of inflammatory activity in chronic periodontitis." (PMID 26251029, 2015). "The aim of this study was to compare and evaluate the systemic levels of CRP in the peripheral blood samples of patients with chronic and aggressive periodontitis, gingivitis, and gingival recessions and compare them with periodontal clinical parameters." (PMID 26346216, 2015). "A study from the USA recorded CRP levels of 2.05 mg/L in aggressive periodontitis patients with generalized form and CRP levels of 1.1 mg/L in patients with localized form." (PMID 26346216, 2015). "The increased serum CRP levels and neutrophils counts in chronic periodontitis subjects suggest an addition to the inflammatory burden of the individual, potentially striking towards an increasing risk of cardiovascular events." (PMID 26346216, 2015). "The bleeding on probing index showed much better positive correlation with the CRP levels compared to the pocket depth index in both periodontitis patient groups, especially in aggressive periodontitis patients." (PMID 26346216, 2015). "Statistical correlations between measured BOP and PD indices and determined CRP levels in periodontitis patient groups, Groups A and B, were established." (PMID 26346216, 2015). "Another study from India showed CRP levels of 7.49 mg/L in aggressive periodontitis patients and CRP levels of 4.88 mg/L in chronic periodontitis patients." (PMID 26346216, 2015). "Serum elastase and CRP are significantly elevated in patients with untreated aggressive periodontitis." (PMID 26346216, 2015). "The statistic analysis showed a significant difference in CRP concentrations between the periodontitis patients and healthy subjects (p = 0.045)." (PMID 26346216, 2015). "Most studies have focused on CRP levels in chronic periodontitis, and very few are conducted on patients with aggressive periodontitis." (PMID 26346216, 2015). "A similar phenomenon to what was found in this study regarding CRP levels in patients with aggressive and chronic periodontitis and gingivitis was also published by other researchers." (PMID 26346216, 2015). "In this study, we show increased CRP-levels in periodontitis which is in accordance with several previous studies." (PMID 26241961, 2015). "The present results demonstrate that diabetic patients with untreated periodontitis present increased circulating levels of markers of inflammation and proinflammatory cytokines (CRP, TNF-α and IL-6)." (PMID 26644840, 2015). "CRP is produced in response to many forms of injury other than periodontitis, such as other infections, trauma and hypoxia, and it is regulated by diverse cytokines." (PMID 26346216, 2015). "BOP showed the best positive correlation with the levels of CRP in the aggressive periodontitis group compared to the chronic periodontitis group." (PMID 26346216, 2015). "Recent evidence has indicated that patients with severe periodontitis have increased serum levels of CRP compared to unaffected control population." (PMID 26346216, 2015). "The patients with gingivitis and healthy gingiva had lower levels of CRP than the patients with chronic periodontitis." (PMID 26346216, 2015).
periodontitis (continued). "CRP, elastase, lipopolysaccharide binding protein, and IL-6 levels were elevated in patients with untreated aggressive periodontitis compared to healthy control group." (PMID 26346216, 2015). "Significantly low levels of CRP were observed in the gingival recessions group compared to the aggressive and chronic periodontitis groups." (PMID 26346216, 2015). "In Netherlands, a study reported the highest CRP levels (1.45 mg/L) in patients with generalized form of periodontitis and CRP levels of 1.30 mg/L in patients with localized form." (PMID 26346216, 2015). "The CRP levels were 5332.62 ± 5051.63 pg/mL in periodontitis patients, 3545.41 ± 3061.38 pg/mL in the gingivitis group, and 3108.51 ± 3574.47 pg/mL in healthy subjects." (PMID 26346216, 2015). "Biomarkers like CRP, pentraxin-3, visfatin, cystatin, and resistin were evaluated for their presence in periodontitis relating to chronic kidney diseases and diabetes." (PMID 24692844, 2014). "Salivary CRP levels in chronic periodontitis group were the highest and CRP levels in healthy subjects were the lowest among the three groups." (PMID 24551806, 2013). "The present study was envisaged to determine the influence of periodontal treatment on the serum CRP & TNF-α level in cardiovascular patients with periodontitis." (PMID 24198887, 2013). "Although periodontitis is a chronic inflammatory disease but some factors of acute inflammation phase are involved in this disease among which is the C-Reactive protein (CRP)." (PMID 24551806, 2013). "If periodontitis can lead to the elevation of CRP & TNF-α levels, then theoretically, periodontal therapy should help in reducing the systemic burden of inflammation." (PMID 24198887, 2013). "Our study is one of the few studies which compared salivary CRP concentrations in healthy subjects and patients with gingivitis and periodontitis." (PMID 24551806, 2013). "The results of the present study showed that salivary CRP concentrations increase in patients with periodontitis comparing to gingivitis and healthy subjects, confirming this theory that salivary CRP is increased in inflammatory conditions." (PMID 24551806, 2013). "Anti-infective periodontal therapy among adult men and women with periodontitis results in modest short-term systemic CRP reductions based on results from 20 randomized controlled trials conducted in 14 different countries across 5 continents." (PMID 24155956, 2013). "In a large meta-analyses of case-control and longitudinal treatment studies CRP levels were significantly higher in subjects with periodontitis as compared to controls." (PMID 24386401, 2013). "Clinical parameters such as OHI-S index and PPD showed a positive correlation with CRP & TNF-α level in both the groups with chronic periodontitis in this study." (PMID 24198887, 2013). "The mean salivary CRP levels were 5332.62±5051.63pg/ml in periodontitis patients, 3545.41±3061.38pg/ml in gingivitis group and 3108.51±3574.47pg/ml in healthy subjects." (PMID 24551806, 2013). "An increasing number of studies are focusing on the relationship between C-reactive protein and periodontitis." (PMID 24286083, 2013). "For instance, levels of CRP are higher in periodontitis compared to healthy patients, and reduction of this marker is observed after periodontal therapy in otherwise healthy individuals." (PMID 24010954, 2013). "The statistic analysis showed a significant difference in salivary CRP concentrations between the periodontitis patients and healthy subjects (P=0.045)." (PMID 24551806, 2013). "Systemic and local chronic inflammatory states, such as periodontitis and MetS, are characterized by an elevated presence of acute-phase proteins such as CRP and fibrinogen, which represent a decisive contribution to the insurgence of atherosclerosis and CVD." (PMID 23009606, 2012).
periodontitis (continued). "It has been shown that elevated CRP levels in patients with periodontitis affects inflammation in atherosclerotic lesions, increasing the risk for cardiovascular and cerebrovascular events." (PMID 22322513, 2012). "Periodontitis produces bacteraemias and the host responds with elevated levels of interleukin-6 (IL-6), known to induce hepatocytes to produce CRP and other acute-phase proteins and pro-coagulant mediators." (PMID 22322513, 2012). "Circulating levels of CRP and IL-6 were significantly higher in the periodontitis subjects with hypertension, than in the control group." (PMID 23009606, 2012). "Serum C-reactive protein levels were measured in 24 patients with moderate periodontitis, 26 patients with severe periodontitis, and 25 periodontally healthy subjects." (PMID 23019501, 2011). "The periodontal parameters (PI, GI, BOP and PPD) were significantly correlated with CRP levels in periodontal patients, especially in the group of patients with severe periodontitis (p<0.001, p<0.001, p<0.001, p<0.0001)." (PMID 23019501, 2011). "The periodontal parameters and CRP levels were significantly higher in the patients with periodontitis." (PMID 23019501, 2011). "CRP, IL-1β, IL-6, and TNF-α have been associated with the presence of various bacterial infections, including periodontitis." (PMID 20407653, 2009). "The aim of the present study was to investigate systemic levels of inflammatory markers of cardiovascular diseases like C-reactive protein and interleukin-6 in patients with chronic periodontitis, in comparison to periodontally healthy individuals." (PMID 20407653, 2009). "Periodontitis can induce a peripheral inflammatory and immune response, as evidenced by elevated concentrations of CRP and IgA antibodies to periodontal pathogens." (PMID 19018303, 2008). "The link between periodontitis and atherosclerotic coronary artery disease seems to stem from both the persistent microbial load and the inflammatory response, as evidenced by elevated levels of systemic inflammatory markers like CRP and IL-6." (PMID 40217896, 2025). "The host’s susceptibility to systemic disorders increases with periodontitis, largely due to the accumulation of gram-negative bacteria and the elevated levels of inflammatory mediators such as C-reactive protein (CRP) and interleukin-6 (IL-6)." (PMID 40916006, 2025). "Moreover, individuals suffering from both chronic periodontitis and cardiovascular disease demonstrate significantly higher serum CRP concentrations and polymorphonuclear neutrophil counts compared to those with periodontitis alone or healthy controls." (PMID 41586318, 2025). "As a key pro‐inflammatory cytokine involved in both RA and PD, IL‐6, alongside CRP, a marker of systemic inflammation, suggests that periodontitis microbiota induced a more intense systemic inflammatory response, mirroring clinical findings in patients with RA and concomitant PD." (PMID 41321261, 2025). "Machine learning analyses indicated moderate discriminative abilities when periodontal inflammation was used to predict systemic inflammation (CRP ≥ 2 mg/L, AUCs of 0.72 and 0.74) and when using systemic health indicators to predict the diagnosis of periodontitis (AUCs of 0.82 and 0.72)." (PMID 40701837, 2025). "The elevated CRP levels observed in the periodontitis cohort support the biological plausibility of this association, as chronic systemic inflammation represents a well-established pathway linking periodontal disease with cardiovascular and neoplastic outcomes." (PMID 41420778, 2025). "Similarly, low birth weight labor is linked to periodontitis through intermediary pro-inflammatory cytokines and chemokines, namely TNF-α, IL-1β, CRP, IL-1, IL-6 and IL-18." (PMID 41394354, 2025). "Furthermore, inflammatory cytokines, such as C-reactive protein, tumor necrosis factor-α, immunoglobulin G, interleukin-1β, and interleukin-6, are released in response to periodontitis." (PMID 40907543, 2025).